CD34 (CD34 molecule)
Diseases named in the same sentence as CD34 in open-access papers (continued):
Sharing a sentence is not in itself a finding about the gene and the disease.
tumor (continued). "In the surgical specimen, tumor cells were positive for STAT6 and CD34." (PMID 36550858, 2022). "The tumor cells exhibited membranous positivity for CD31 and CD34 immunomarkers." (PMID 35252055, 2022). "As indicated in the results section, we found that reduced/absent expression of CD34 was associated with degree of malignancy of ISFT and tumor progression." (PMID 35712477, 2022). "The tumor immunohistochemistry results were B‐cell lymphoma 2 (BCL‐2) positive, focal CD34 +, focal cytoplasmic CD99+, epithelial membrane antigen (EMA) and Panker negative, actin negative, S100 protein‐negative, Papanicolaou and Block cell with a positive result for malignant tumor cells." (PMID 35414906, 2022). "In the melanoma cell line B16F10 spontaneous metastasis model, TMP inhibited tumor metastasis through its antiangiogenic activity by decreasing the expression of CD34 and VEGF in the primary tumor tissue and reducing the number of metastase nodi on the lung surface." (PMID 34975475, 2021). "Our results demonstrate significantly increased CD34+ areas, suggesting increased tumor angiogenesis and confirming tumor growth in the absence of L2pB1 cells." (PMID 34630396, 2021). "Immunohistochemically, the tumor cells were positive for vimentin, smooth muscle actin (SMA), CD34, and endothelial membrane antigen (EMA) and negative for desmin, erythroblast transformation-specific related gene (ERG), myoglobin, S-100 protein, HMB-45, melan-A, CD117, AE1/AE3, and CAM5.2." (PMID 34193249, 2021). "Vascular‐like structures were detected within the tumors and they were GFAP+, but CD34‐, suggesting that they were formed by tumor cells, but not from vascular endothelial cells." (PMID 34213079, 2021). "However, it is also possible that CD34-positive tumors are derived from CD34+ SFCs while CD34-negative tumors have completely different origins; if such is the case, CD34-positive tumors could be considered a new tumor entity derived from CD34+ SFCs that are associated with better prognoses." (PMID 34326362, 2021). "The expression of CD34 and αSMA was histopathologically analyzed in tumor and DLM tissue of 10 primary VSs with and without a DLM." (PMID 34942951, 2021). "Tumor tissue expression of CD31, CD34, and CD105 was analyzed." (PMID 33535525, 2021). "In areas surrounding the tumor without visible invasion of tumor cell clusters, the adventitia of blood vessels still displays CD34 staining in almost the entire adventitia circumference, as in normal blood vessels." (PMID 34359889, 2021). "ENG shows affinity for “newly forming” angiogenic endothelium, whereas CD34 and CD31 react not only with angiogenic vessels, but also with the endothelium of normal vessels; ENG is thus superior to CD34 and CD31 for the evaluation of tumor angiogenesis." (PMID 34944885, 2021). "In summary, our data demonstrate the critical role of Mettl3 in driving BCa progression, as featured by expediting angiogenesis surrounding tumor cells, and unveil a previously unrecognized signaling axis involving Mettl3-TEK-VEGF-A-CD31/CD34 in bladder malignancy." (PMID 33681207, 2021). "Both populations elicited high effector activity against CD19+ tumor cells but not CD19– cells, underlining that CD34 epitope-based selection preserved functionality of esCAR T cells." (PMID 33526841, 2021). "Furthermore, consecutive sections of allograft tumor tissues, stained with PAS, CD34, VE-cadherin, or EphA2, were scanned to count the number of MV (CD34+/PAS−) and VM (CD34+/PAS−)." (PMID 34221978, 2021). "Encouragingly, SKLB325 could significantly suppress the tumor‐derived VEGF levels in the circulation of mice and inhibit the expressions of CD34 and CD105 in renal cell orthotopic models, which were both the angiogenesis and proliferation markers." (PMID 33634984, 2021).
tumor (continued). "In most cases, there is negative or focal positive CD10 expression and positive CD34 expression, indicating that the tumor thrombus originates from smooth muscle cells rather than endometrial stromal cells or vascular endothelial cells." (PMID 33429819, 2021). "Although pathological examinations revealed plenty of vessels in parenchymal tissue and high expression levels of angiogenesis biomarkers, including CD34 and VEGF; blood vessels inside the tumor were either small and thin-walled, or had a significantly thickened and hyalinized wall." (PMID 33995279, 2021). "In this context, >90% of SFT express CD34 and STAT6, while a smaller percentage of tumours may be positive for CD99 (70%), EMA (20%), smooth muscle actin (20%) and BCL-2 (30%)." (PMID 34849218, 2021). "Specifically, the tumor initiation ability of SCC CSCs measured by serial limit-dilution transplantation assays seems to be governed by α6β1 but not CD34, as only α6hiβ1hi populations, regardless of CD34 expression level, can initiate secondary tumors." (PMID 34715893, 2021). "We think that it is ideal to use CD34-humanized mice or PBMC-reconstituted mice, this setting would better inform on the efficacy of the combination since a PD-1 blocker would then target T cells present in the tumor." (PMID 34576141, 2021). "On immunohistochemistry, the tumor cells had typically strong and diffuse positivity for vimentin and BCL2, focal positivity for CD34, and weak diffuse positivity for CD99 but negativity for cytokeratins AE1–AE3, actin HHF35, actin 1A4, calponin, caldesmon, desmin, S-100 protein, and collagen IV." (PMID 34211794, 2021). "Immunohistochemical staining indicated the tumour was positive for CD34, STAT6, vimentin and bcl-2, but negative for cytokeratins, D2-40 and S-100." (PMID 33623662, 2021). "First, we categorized clustered data into tumor and stromal populations using a panel of markers for each (epithelial: AQP1, AQP2, EPCAM; endothelial: PLVAP, CD31, CD34; fibroblast: PDGFRα, PDGFRβ; immune: CD45; tumor cell: CXCR4, VIM, KRT18, PAX8, PAX2, CA9, CD10)." (PMID 34884982, 2021). "We showed that the expression of proteins specific to ECs (ACE+, VWF+), their differentiation (CD31+, CD 133+, CD105+, CD34-), their adhesion properties (ICAM-1+, VCAM-1+, CD62-L+), and their barrier formation (ZO-1+) were all downregulated in tumor-derived ECs." (PMID 34445568, 2021). "The tumor was diagnosed as a desmoid tumor based on positive immunohistochemical staining for β-catenin and negative staining for c-kit, CD34, platelet-derived growth factor (PDGFRα), and Discovered on GIST-1 (DOG-1)." (PMID 34526110, 2021). "In comparison, icSFT/HPCs displayed occasional foci with tumor vasculature that were negative for CLDN5 but strongly positive for CD34." (PMID 33799999, 2021). "With regard to the differential diagnosis of this tumor, NTRK-rearranged tumors may be a consideration given the monomorphic spindle cells, CD34 expression, and focally sclerotic background." (PMID 34256767, 2021). "Immunohistochemistry of consecutive paraffin sections of HCC tissues containing portal vein cancerous thrombi by using Abs again CD34 and CD3 showed that endothelial cells or endothelial vessels act as a potential barrier to protect T lymphocytes to contact with tumor cells." (PMID 33928829, 2021). "Immunohistochemical markers CD31, CD34 and ERG confirmed the vascular nature of the tumor." (PMID 33593408, 2021). "In our case, the tumour cells are positive for BCL-2, CD34 and STAT6." (PMID 34849218, 2021). "Tumor tissues were immunohistochemically analyzed for the expression of Ki67, CD45, CD4, CD8, PD1, PD-L1, PD-L2 and CD34, by Nanostring nCounter PanCancer Immune Profiling Panel as well as a comprehensive methylome profiling using the Infinium MethylationEPIC BeadChip." (PMID 33953302, 2021). "CD133, CD44, CD34, FOXP3, PDL1, LDH, and VEGF for assessing tumor cell inhibition." (PMID 37305162, 2021).
tumor (continued). "In this case, the tumor cells were positive for CD31 and CD34 stain with focal positivity." (PMID 33509230, 2021). "Immunohistochemically, tumor cells demonstrated membranous positivity for CD99, positivity for Nkx2.2, focal positivity for S100 and negativity for desmin, myogenin, MyoD1, cytokeratin (AE1/AE3), CD31, CD34, CD3, CD20, and CD1a." (PMID 34749732, 2021). "Immunohistochemically, the tumor cells lacked of reactivity with CD34; CK5/6, EMA, SOX10, S100, desmin, SMA, MDM2 and GFAP." (PMID 32164724, 2020). "No positive staining for CD34 was observed in PC-3 or DU145 tumour samples (parental and holoclone-derived) (data not shown for DU145)." (PMID 32647229, 2020). "On immunostaining, the tumor was positive for vimentin, CD34, and Bcl-2, and negative for α-smooth muscle actin (α-SMA)." (PMID 31848901, 2020). "Rosato and colleagues studied TNBC using the patient-derived xenograft (PDX) tumor line MC1 in CD34+ HSC-engrafted NSG mice in comparison to non-humanized NSG mice." (PMID 32570871, 2020). "Although PMTs have been reported to be negative for CD68, S-100, and CD34 staining, in this study, and our previous study, the tumor cells of PMTMCTs and PMTMECTs showed consistent diffuse positive staining for CD68 and variable focal positive staining for S-100 and CD34." (PMID 32049812, 2020). "It is suggested that the stromal response of the host tissue is the most important phase in the development and growth of tumor invasion and CD34 is evident in healthy tissues, however α-SMA was not a feature of normal tissues." (PMID 33383808, 2020). "The depth of tumor invasion was 3.7 ± 3.8 mm, 6.8 ± 5.1 mm, and 12.5 ± 2.9 mm in the absence of DCs with weak CD34 expression, single and multiple ones, respectively (p=0.04)." (PMID 32849870, 2020). "The tumor cells were robustly and diffusely positive for Trk, S100-protein, CD34, and nestin, but negative for CD56, SMA, desmin, myogenin, STAT6, EMA, CK, CD1a, CD21, CD35, CD43, WT-1(c-terminal), MelanA, HMB45, BRAF, and ALK." (PMID 32957984, 2020). "Absence of CD34+ fibroblasts in the tumor stroma significantly correlated with the presence of α-SMA+ myofibroblasts (p = 0.010), positive lymph node status (p = 0.004), and pN stage (p = 0.006)." (PMID 32435886, 2020). "For the diagnosis of BPDCN, the tumor should be negative for other myelomonocytic, NK, T, and B lineage markers (CD34, CD8, MPO, lysozyme, PAX5, CD20, CD79a, EBV, and T-cell receptor protein)." (PMID 31752482, 2020). "To evaluate angiogenesis in patients with ccRCC, we sought to determine first whether a correlation exists between the tumor’s grade, VEGF-A positivity and MVD calculated by the CD34 labeling." (PMID 32620162, 2020). "Tumor cells were immunohistologically positive for α-smooth muscle actin and h-caldesmon; partially positive for desmin; negative for c-kit, CD34, DOG-1, and the S-100 protein; and showed a Ki-67 labeling index of 70–80%." (PMID 33006746, 2020). "Expression of vascular markers CD31, CD34 and ERG confirmed endothelial lineage of the tumor cells." (PMID 32977811, 2020). "Immunohistochemical staining for tumor cells revealed desmin, α-smooth muscle actin (αSMA), and h-caldesmon to be diffusely positive, while c-kit, S100, CD34, CAM5.2, EMA, CD163, and DOG1 were negative." (PMID 32648231, 2020). "The expression of CD34 was not limited in the entity of tumors, but positive in cytoplasm or surrounding the nucleus, even positive around tumor edges." (PMID 32058680, 2020). "Flow cytometry analysis revealed that approximately 35.2 ± 2.3% of tumour cells were CD34 and α6-integrin positive, while 31.7 ± 1.9% of the cells were CD34 positive and α6-integrin negative." (PMID 33123267, 2020). "In the first published report, authors defined VM as positive pancytokeratin, to highlight tumor cells, and negative CD34 lining." (PMID 32102317, 2020).
tumor (continued). "Analysis of controls, namely the endothelial cell-surface membrane protein CD34 and cytosolic α-tubulin, showed comparable positive CD34 staining and negative α-tubulin staining in both tumour and normal tissues." (PMID 32921792, 2020). "Astonishingly, among 145 ILC cases, there was no single one with at least partial preservation of CD34+ fibroblasts in the tumor stroma, contrary to our experience." (PMID 32435886, 2020). "We probed for AQP1 and CD34 (to identify endothelial cells) and stained with hematoxylin and eosin (HE) to identify tumor and nontumor areas of the specimens." (PMID 32253832, 2020). "A previous study that used a chemical carcinogenesis protocol (DMBA/TPA) demonstrated that SCC cells enriched for CD34 more effectively produce secondary tumours upon transplantation compared to the CD34-negative cells." (PMID 33123267, 2020). "Immunohistochemically, the tumor cells show variable positivity for D2-40, CD68, CD34, and SMA." (PMID 32316685, 2020). "By well-controlled, routine immunohistochemical stains, the tumor cells were immunoreactive for vimentin, while they were negative for actin, desmin, S-100 and CD34 antibodies." (PMID 32605652, 2020). "The immunohistochemical findings demonstrated that the tumor cells were positive for vimentin, CD34, and actin but negative for chromogranin A." (PMID 32441904, 2020). "Although the pan-endothelial markers, such as CD31 and CD34, were generally applied to evaluate tumor vascularity, they did not differentiate newly formed and preexisting vasculature." (PMID 33062071, 2020). "On the contrary, the CD34 marker has been found to be negative in the inflamed tissues present around the tumor stroma." (PMID 33383808, 2020). "The changes from TCs/CD34+SCs to stromal cells expressing αSMA in this type of advanced neoplasm cannot be well demonstrated, unlike in the early stages of repair through granulation tissue, in which follow up is possible." (PMID 33353193, 2020). "In this case, tumor cells were positive for desmin, αSMA, and h-caldesmon and negative for c-kit, S100, CD34, CAM5.2, EMA, CD163, and DOG1, supporting the diagnosis of PHL." (PMID 32648231, 2020). "Mice were generated by transplantation of SK-BR-3 tumor cells with (HTM) or without (TM) the additional transplantation of CD34+ HSC derived from CB." (PMID 32799890, 2020). "Furthermore, IHC on the xenografts was carried out using CD34 and VEGF, which are markers for tumor angiogenesis." (PMID 32321509, 2020). "In the ultimate formula, mature stroma, weak α-SMA, low microvascular density (CD34) and higher TIL-stromal ratio stood for favorable prognostic indicators while strong α-SMA, lower TIL-stromal ratio and higher stromal-tumor ratio stood for worse prognostic indicators." (PMID 31299011, 2019). "CSCs have been identified and isolated, based on the expression of specific molecules, such as CD24, CD34, CD44, CD133, and aldehyde dehydrogenase (ALDH), and are able to regenerate tumor mass from a small number of cells when implanted into immunodeficient mice." (PMID 31013960, 2019). "We next examined the expression and distribution of CD34 and CXCR4 in the tumor and stroma areas." (PMID 31336612, 2019). "Immunohistochemistry demonstrated that the tumor cells were positive for CD34, STAT6, vimentin, and Bcl-2, and negative for α-SMA, S100, and EMA." (PMID 31687030, 2019). "After staining for CAIX and CD34, 18 of the 403 patients were excluded due to insufficient tumour tissue (n = 9) and excess of non-specific background staining (n = 9)." (PMID 31011231, 2019). "Positive CD34 immunoreactivity is the key characteristic of this rare tumor, which should be negative in PF except for vascular endothelial cells." (PMID 31360694, 2019). "Immunostaining showed that the tumor was positive for CD 31 and D2-40 and was negative for CD34 and Factor VIII." (PMID 30923959, 2019).
tumor (continued). "It would be interesting to find out whether TERF1-tsi is expressed in a subset of human CD34+ HSC population and whether its expression is downregulated during tumor progression." (PMID 31877678, 2019). "Based on immunohistochemical examination, the tumour cells were positive for CD34, Bcl2, vimentin, and CD99 and negative for desmin and S-100." (PMID 31391089, 2019). "However, CK (AE1/AE3), E-cadherin, ER, PR, CD34, S-100 and CD10 were negatively expressed in the tumor tissue." (PMID 31474003, 2019). "In the present cases of SC/PL, the tumor spindle cells were positive for CD34 and negative for S-100 protein." (PMID 31041916, 2019). "Our findings suggest that (hCB)-CD34+ NSG mice are transient and/or incomplete carriers of the human immune system and, therefore, represent a suboptimal tool to study the interaction between tumor and immune cells." (PMID 31536492, 2019). "Tumor cells exhibit no strong diffuse staining for CD34 and are basically negative for AE1/AE3, Bcl-2, CD34, CD99, CD117, Factor VIIIR Ag, S-100 protein, and STAT6." (PMID 30206803, 2019). "The tumor cells were positive for DOG1 and sporadically positive for CD34 and CD117." (PMID 31647020, 2019). "Immunohistochemical studies showed that the tumor cells were positive for CD31, CD34 and D2–40." (PMID 31277673, 2019). "In all of our MFB cases, the tumor cells were immunoreactive for CD34, desmin, SMA, and ER and negative for cytokeratin, p63, CD68, and beta-catenin." (PMID 30989009, 2019). "In addition, we found that 4/10 GIST lesions showed weak TFE3 positivity, suggesting it can be a candidate marker for differentiating between these two tumor types along with CD117, Dog1 and CD34." (PMID 31043173, 2019). "Immunohistochemical staining showed that the tumor was negative for CD34, c-kit, and S-100 and positive for desmin and α-smooth muscle actin." (PMID 31781464, 2019). "Tumor tissue from control samples displayed high proliferation index, as evaluated by Ki67 nuclear expression, low apoptotic index, as evaluated by TUNEL assay and high neo-angiogenesis, as detected by CD34 expression, as compared to CBP treatment." (PMID 31419989, 2019). "Due to low numbers of CD34+ cells (1.5–3.4%11) and especially low NBC numbers in the transplant it is furthermore necessary to apply sensitive tumour cell analysis methods such as quantitative RT-PCR to analyse clinically relevant samples, which will be addressed in future studies." (PMID 31217534, 2019). "We found that TFF1 exhibited lower expression while MMP9 and CD34 showed higher expression in tumour tissues compared than in adjacent non-cancerous tissues." (PMID 30612555, 2019). "Immunohistochemical analysis showed the tumour cells were positive for ER, PgR, CD34,Desmin, CD99, BCL-2 and negative for H-caldesmon, SMA, c-Kit, S100 protein, MNF116,HMB45 and melan A. Less than 2% of cells were positive for Ki67." (PMID 31131129, 2019). "Immunohistochemically, the tumor cells were diffusely positive for CD34, STAT-6 and FLI-1, but negative for pan-cytokeratin, CAM5.2, p63, S100 protein, CD31, SMA, and calponin." (PMID 30777087, 2019). "MVD is determined by counting CD34-positive vessels, since CD-34 is a vascular endothelial cell proliferation marker and only expressed in the vascular endothelial cells of tumor tissues and not in the vessels of healthy tissues." (PMID 29196964, 2018). "There has been a study that attempted to show direct biological correlates for the texture heterogeneity; it demonstrated correlation between the tumor heterogeneity as measured via texture analysis on CT images, with markers of hypoxia and angiogenesis, such as GLUT-1 and CD34." (PMID 29596522, 2018). "Immunohistochemical analysis of the tumor cells showed positive results for CD34 and vimentin but negative for CD31, epithelial membrane antigen (EMA), α-smooth muscle antibody (SMA), desmin, and S-100." (PMID 30284069, 2018).